EPOR (erythropoietin receptor)
Diseases named in the same sentence as EPOR in open-access papers (continued):
Sharing a sentence is not in itself a finding about the gene and the disease.
tumor (continued). "Taken together, these results question the hypothesis that there is functional relevance to EpoR mRNA transcription in tumours." (PMID 18349818, 2008). "Therefore, a recent study suggesting high-level EpoR expression in head and neck tumours correlated with tumour progression and worse survival in patients administered ESAs most likely identified the well-know association of HSP70 and worse prognosis." (PMID 18349818, 2008). "EPOR transcript levels in tumours and tumour cell lines were low in comparison with bone marrow and were equivalent to, or lower than, levels in normal tissues of tumour origin." (PMID 18349818, 2008). "Kayser and Gabius26 first suggested that human tumours express EpoR." (PMID 17394500, 2007). "The immature nature of tumour vessels compared with mature hepatic vessels may be related to the selective expression of EpoR." (PMID 17394495, 2007). "The reason for this selective expression of EpoR in the tumour vessels is unclear." (PMID 17394495, 2007). "The expression of EpoR in tumour vascular endothelium suggests that Epo may affect the tumour microenvironment, perhaps by stimulating tumour angiogenesis." (PMID 17394495, 2007). "Evidence for a functional Epo-EpoR system has been reported by several groups: intratumoural and intraperitoneal injections of solube EpoR or neutralizing monoclonal antibody to EpoR resulted in tumour growth delay and inhibition of angiogenesis." (PMID 16288305, 2005). "However, other studies contradicted these findings and even suggested that the level of EPOR in the cirrhotic tissue could be correlated with tumor cell differentiation and a favorable outcome." (PMID 36961524, 2023). "This indicates that our results translate from preclinical research to human (lung) cancer patients and that targeting EPOR specifically in cancer cells may provide a new approach to control the expression of mitochondria in cancer cells and thus, tumor metabolism." (PMID 36052260, 2022). "New EPO/EPOR target genes in cancer cells could serve as markers for various means of monitoring both disease activity and cell responses to various therapies, including the administration of rHuEPO to tumor patients." (PMID 34281163, 2021). "Finally, our results suggest blocking the access to EPOR on tumor cells during ESAs treatment may be helpful to prevent tumorigenicity and not to affect erythropoiesis." (PMID 29137269, 2017). "Finally, we characterized the role of EPO/EPOR in hypoxia induced tumor progression." (PMID 29137269, 2017). "Based on the current literature, the influence of EPO/EPOR on different cancer types appears to be variable and remains incompletely understood and more functional studies are needed to determine whether EPOR activation modifies tumor cell growth." (PMID 28415825, 2017). "Also, concern has been raised whether endothelial cells that express EPOR could be activated by rhEPO exposure to induce angiogenesis and thereby indirectly promote tumour growth." (PMID 27581518, 2016). "It is argued that the binding of exogenous rhEPO with EPOR might attenuate tumour growth by decreasing hypoxia (through erythrocyotosis), and thereby HIF, and the subsequent expression of downstream molecules that facilitate angiogenesis and other features of cancer progression." (PMID 23305401, 2013). "The alternative argument is that binding of exogenous rhEPO with EPOR might, theoretically, initiate autocrine/paracrine effects that will promote tumour progression through inhibiting apoptosis, accelerating proliferation, promoting angiogenesis and enhancing drug resistance." (PMID 23305401, 2013). "Thus further investigation into this, and correlating the tumor hypoxic status to EPO/EPOR expression may be warranted." (PMID 24004818, 2013). "However, the presence of the EpoR on tumor cell lines has led to disparate interpretations." (PMID 23052842, 2013).
tumor (continued). "Thus, low level protein production and/or inefficient surface translocation of EpoR may be limiting factors for Epo-EpoR responses in tumor cells and cell lines." (PMID 23861852, 2013). "Preclinical topics include (i) whether tumour cells express EpoR and could be directly stimulated to grow by ESA exposure and (ii) whether endothelial cells express EpoR and could be stimulated by ESA exposure to undergo angiogenesis and indirectly promote tumour growth." (PMID 22395661, 2012). "Because EPOR has been confirmed in various endothelial cells, especially including brain capillary endothelial cells, rhEPO can directly stimulate angiogenesis of both EPOR positive and negative tumors, which in turn provide a growth advantage to tumor cells in vivo." (PMID 22086127, 2012). "A number of recent studies showed preferential expression of EpoR in cancer-initiating (stem) cells, enabling a novel explanation for the negative clinical associations of high sEpo (or administered rhEPO) through the direct effects on tumor cells." (PMID 21829709, 2011). "Kayser and Gabius16 first suggested that human tumours may express EpoR." (PMID 17394495, 2007). "One of these tyrosine kinase receptors, Erythropoietin Receptor (EPOR), plays a critical role in CRC progression by enhancing tumour metabolism, angiogenesis, proliferation, and growth." (PMID 41514679, 2026). "Based on our results from the tumor and surrounding healthy tissue samples, HIF1A emerged as the primary determinant of EPO, EPOR and JAK2/STAT5A signaling pathway expression in ccRCC." (PMID 40332447, 2025). "Other studies have found that these factors can also affect the prognosis of TNBC, including tumor-infiltrating lymphocytes (TILs), CD103 iTIL density, positive prolactin receptor, adipophilin, erythropoietin receptor and increased Bcl-2 expression." (PMID 38827797, 2024). "Transcriptomic analyses and mapping of EPO/EPOR target genes are also necessary for tumor and normal cells, on which only signaling and the effect of EPO/EPOR have been described so far, e.g., protective, antiapoptotic, trophic, and other." (PMID 34281163, 2021). "Ephrin-type B-receptor 4 (EPHB4) was also identified as an alternative EPOR that triggers downstream signaling via STAT3 and promotes recombinant human EPO-induced tumor growth and progression." (PMID 34281163, 2021). "When EPOR signaling was blocked by EPOR knockdown or soluble EPOR against EPO, it inhibited tumor growth and invasion, and resulted in cell apoptosis." (PMID 32015330, 2020). "Self-sustainable EPO/EPOR signaling was a mediator of hypoxia induced cell growth in dual EPO and EPOR-positive NSCLC tumor." (PMID 29137269, 2017). "EPOR is also expressed in various cancer cell lines (including NSCLC) and in human tumor tissues including stromal components such as the vasculature." (PMID 24155958, 2013). "Thus, examining whether tumour cells express ESA-responsive EpoR has been of interest." (PMID 22395661, 2012). "Thus, EPOR may play a role in tumor proliferation, apoptosis, and angiogenesis." (PMID 22639817, 2012). "In EPOR-R129C tumors, there was a significant increase in phospho-ERK1/2 positive tumor cells compared to vector controls (P<0.0001)." (PMID 17579721, 2007). "Higher EPOR expression is associated with unfavourable prognosis both for MYCN non-amplified NB tumours and in relapsed tumours." (PMID 41511287, 2025). "Studies showed that functional EPO receptor signaling was critical for the tumor-promoting growth effects of EPO through in vitro and in vivo experiments, indicating that EPOR expression was positively correlated with the expression of the mitochondrial marker VDAC1 in human NSCLC patient biopsies." (PMID 37746281, 2023). "Further, EPOR was found to play a non-negligible role in tumor immunity, and a correlation of EPOR with miRNAs, TMB, MSI, and MMR genes and methyltransferases was confirmed to some extent." (PMID 35359375, 2022).
tumor (continued). "Similar to tumor growth, EPO treatment did not alter cellular respiration but the loss of EPOR reduced cellular respiration in A549 tumors." (PMID 36052260, 2022). "Growing evidence indicates that EPOR is also expressed in nonerythroid cells, such as kidneys, heart, brain, and various tumor cell lines." (PMID 32908942, 2020). "Previous studies have demonstrated that EPOR is expressed in nonerythroid cells, such as the brain, kidneys, heart, and various tumor cell lines." (PMID 32908942, 2020). "Both patients were found to be negative for mutations in erythropoietin, erythropoietin receptor, HIF-1α, janus kinase 2, prolyl hydroxylase, succinate dehydrogenase B/C/D, and von Hippel-Lindau genes in circulating leukocytes and resected tumor tissues." (PMID 31185588, 2019). "EPOR protein expression and EPO level were notably increased in the patient’s tumor tissue as well." (PMID 29534684, 2018). "Even more interestingly, EPO accelerated the tumor growth of rat prolactinoma MMQ pituitary adenoma xenografts lacking EPOR via the enhancement of angiogenesis in vivo, without a direct effect of EPO on MMQ cells in vitro." (PMID 28703764, 2017). "Furthermore, the phosphorylation levels of EPOR and STAT5 in these 14 tumor specimens were significantly increased compared to that in the remaining 21 tumor specimens from the patients whose serum EPO was at low level or remained unchanged after surgery." (PMID 29137269, 2017). "In summary, we have illustrated EPO could be directly secreted from the tumors of a subgroup of NSCLC patients, and the tumor derived EPO was capable of promoting the dual EPO and EPOR-positive NSCLC progression." (PMID 29137269, 2017). "In this regard, EPO induces angiogenesis in chemically induced murine hepatic tumors and accelerates the growth of EPOR-negative Lewis lung carcinoma cells by promoting tumor angiogenesis in vivo." (PMID 28703764, 2017). "In this study, we did not observe changes in tumor capillary densities after local EPO blockage or EPOR knockdown (data not shown)." (PMID 29137269, 2017). "The systematic identification of pathway differences and sensitivities of EPOR signaling in CFU-E and H838 cells revealed potential targets for intervention to selectively inhibit EPO-induced signaling in the tumor cells but leave the responses in erythroid progenitor cells unaffected." (PMID 27494133, 2016). "Although Epo and its receptor EpoR were originally believed to have an exclusive role in erythropoiesis, they are also expressed in many non-hematopoietic cells including certain tumor tissue." (PMID 27543111, 2016). "In EpoR-negative Ht-29 xenografts tumor development was slower as demonstrated by reduced mitotic index after Epo treatment." (PMID 27543111, 2016). "Taken together, these data support the conclusions derived from flow cytometry-based analysis of EpoR in that no expression or function was detectable in tumor tissues but EpoR expression and function was observed in EPCs at this stage of differentiation." (PMID 25807104, 2015). "More recent, detailed studies have reported that tumor cell-lines, tumor biopsies, and endothelial cells did not contain increased levels of EpoR mRNA, or protein compared with normal tissues and that there was no amplification of the EpoR gene in tumor cells." (PMID 25807104, 2015). "The lack of EpoR expression suggested that EpoR was not induced in tumor cells during disease progression and was also not induced in response to treatment." (PMID 25807104, 2015). "Although early literature was inconsistent with functional EpoR expression in non-hematopoietic cells, including tumor cells and cell-lines, safety signals reported in some recent clinical studies re-ignited interest in this question." (PMID 25807104, 2015). "Unlike known oncogenes such as HER2 and EGFR, EpoR mRNA is not elevated when tumor samples are compared with normal samples." (PMID 24337485, 2014).
tumor (continued). "Even more interestingly, EPO accelerated the tumor growth of MMQ pituitary adenoma xenografts lacking EPOR via enhancement of angiogenesis in vivo, without a direct EPO effect on MMQ cells in vitro." (PMID 25426117, 2014). "In a survey of 61 non-hematopoietic tumor-cell lines, only one cell line had detectable (low level) EpoR protein on the cell surface." (PMID 24337485, 2014). "On the one hand, there are papers pointing to the proliferative response of cancer cells after rHuEPO treatment; on the other hand, some tumor cells, in spite of evidence of EPOR functionality, did not exhibit a growth response." (PMID 25426117, 2014). "When a specific and sensitive EpoR antibody is applied, EpoR is low to undetectable on immunostaining in non-myeloid cells or tumor cells which is consistent with the low levels of EpoR transcripts in those cell types." (PMID 24337485, 2014). "In this regard, EPO xinduced angiogenesis in chemically induced murine hepatic tumors and accelerated the growth of EPOR negative Lewis lung carcinoma cells by promoting tumor angiogenesis in vivo." (PMID 25426117, 2014). "While early studies suggested EpoR transcripts were expressed exclusively in the erythroid compartment, low-level EpoR transcripts were detected in nonhematopoietic tissues and tumor cell lines using sensitive RT-PCR methods." (PMID 23861852, 2013). "Multivariate analysis (including standard prognostic variables, such as age, gender, tumor stage and smoking history) also indicated that pretreatment EPOR levels predicted outcome independent of other variables (p = 0.031)." (PMID 24155958, 2013). "A western survey with A82 of 66 different tumor cell lines demonstrated that EpoR protein was at no/low levels in most tumor cell lines and that the lines with the highest levels did not signal with ESAs." (PMID 23861852, 2013). "In tumor cell lines and normal human tissues examined with a specific and sensitive monoclonal antibody to human EpoR (A82), little/no EpoR protein was detected and it was not functional." (PMID 23861852, 2013). "In the absence of definitive antibody reagents to detect EpoR protein, in vitro experiments were designed with the goal of detecting functional responses with tumor cell types following rHuEpo addition." (PMID 23861852, 2013). "As suggested in other recent studies, however, the overall direct effect of EPO/EPOR signaling on tumor progression and therapy is not straightforward." (PMID 24155958, 2013). "In a more recent study, we also found that rHuEPOα did not modify the in vitro proliferation of EPOR expressing A431 tumor cells but enhanced the effect of irradiation on proliferation, apoptosis and clonogenic capacity." (PMID 24155958, 2013). "Taken together these results suggest that high level expression of EpoR is not a general property of either normal or tumor tissues or tumor cell lines." (PMID 23861852, 2013). "Studies in other tumour cell lines have also shown little/or no expression of EpoR protein and/or a lack of functional EpoR." (PMID 22395661, 2012). "Overall, the balance of current evidence does not support an effect of ESAs on either activating EpoR on tumour cells or indirectly stimulating disease progression via angiogenesis." (PMID 22395661, 2012). "Additional studies indicate that the EpoR gene is not amplified in tumour cells and that Epo exposure does not induce tumour cell line proliferation or affect mortality in many animal tumour models." (PMID 22395661, 2012). "If blood vessel endothelial cells express EpoR, then ESA exposure could hypothetically stimulate neovascularisation or angiogenesis; blood vessel growth in a tumour could then enhance tumour proliferation." (PMID 22395661, 2012). "EPOR expression was measured in 12 paired samples of tumor tissue and adjacent non-tumor oral tissue (from early to late stage) using Q-RT-PCR." (PMID 22639817, 2012).
tumor (continued). "In a study performed in primary human tumour samples from multiple epithelial tumour types, no cell surface or functional EpoR was detected." (PMID 22395661, 2012). "A post-hoc analysis of EpoR expression in tumour cells from ESA-treated and control patients suggested that locoregional progression-free survival was poorer in ESA-treated patients with EpoR-positive tumours." (PMID 22395661, 2012). "Recent studies have also found that tumour cell lines and tumour biopsies do not contain increased levels of EpoR mRNA transcripts compared with normal tissue controls and that the EpoR gene is not amplified in tumour cells." (PMID 20051958, 2010). "This suggests that there is no selective advantage for tumours to overexpress EpoR and questions the functional relevance of EpoR gene transcription in tumours." (PMID 18349818, 2008). "The notion that EpoR was overexpressed in tumours and that rHuEpo enhanced tumour progression has been confounded by the finding that antibodies used to detect EpoR are nonspecific and additionally bind non-EpoR proteins, including HSP70." (PMID 18349818, 2008). "For each of the five probe sets for EPOR on the HG-U133 Plus 2.0 array, levels of EPOR transcripts in tumours were not significantly elevated above levels found in the normal tissue counterpart (data not shown)." (PMID 18349818, 2008). "They showed that Epo was not detectable in the normal or cirrhotic liver tissues without tumours, while immunoreactive EpoR was detectable in the endothelium of intervening vessels of all hepatic tumours." (PMID 17394495, 2007). "No immunoreactive EpoR was discernible in the wall of the hepatic vasculature in the cirrhotic tissues adjacent to the tumours." (PMID 17394495, 2007). "To investigate whether the EpoR on LLC cells was functional, we determined the effect of in vitro darbepoetin treatment on tumour cell proliferation using the MTT assay." (PMID 15999100, 2005). "A direct effect of darbepoetin on EpoR-expressing tumour cells is ruled out in this case, as the cells were shown not to respond to the hormone." (PMID 15999100, 2005). "The tumour cells employed in that experiment did not express the EpoR, ruling out a direct antitumour effect." (PMID 15999100, 2005). "The lack of HIF1A protein decreased the expression of EPOR in tumor tissue (p = 0.0246)." (PMID 40332447, 2025). "To explore the correlation between EPOR gene expression and immune infiltration, we first analyzed the correlation of EPOR with six infiltrating immune cells (B cells, CD4 + T cells, CD8 + T cells, macrophages, neutrophils, and dendritic cells) and tumor purity in the TIMER2.0 database." (PMID 35359375, 2022). "In addition, the results of this study indicate that EPOR plays a non-negligible role in tumor immunity, which provides a new direction for tumor research." (PMID 35359375, 2022). "Taken together, due to the widespread use of nonspecific anti-EPOR antibodies that may provide false positive staining, the tumor-promoting effects of the EPO/EPOR axis have remained an outstanding issue." (PMID 35694408, 2022). "This is important, because it may be possible to use a tumor’s EpoR to target a drug to a tumor and not damage the surrounding tissues." (PMID 27543111, 2016). "Furthermore, EpoR was not detectable on human tumor cells isolated directly from multiple epithelial tumor types." (PMID 25807104, 2015). "In addition, according to two different criteria, flow cytometry and Western blotting, no EpoR was detected in any tumor sample." (PMID 25807104, 2015). "When using a specific monoclonal anti-EpoR antibody suitable for Western blotting (such as monoclonal anti-EpoR antibody A82), a 59-kDa EpoR protein can be detected in erythroid cell extracts but not in tumor biopsies or most tumor-cell lines." (PMID 24337485, 2014). "However, in controlled experiments, no binding of either 125I-rHuEpo or of specific anti-EpoR antibodies to non-hematopoietic cells or primary-tumor cells was detected." (PMID 24337485, 2014).